SLC19A2 (solute carrier family 19 member 2)
Description:
High-affinity transporter for the intake of thiamine. Mediates H(+)-dependent pyridoxine transport.
Synonyms: ThTr1; TC1; THT1; TRMA; THMD1
Tractability: Small molecule: a structure with a bound ligand is known. Antibody: UniProt places it where antibodies can reach, with high confidence; its Gene Ontology location is reachable by antibodies, with high confidence; UniProt predicts a signal peptide or a membrane-spanning region. PROTAC: ubiquitination databases record sites on it; a small molecule that binds it is known.
Target class: SLC19 family of vitamin transporters; Transporter; Electrochemical transporter; SLC superfamily of solute carriers
Gene: Protein-coding gene on chromosome 1 (169,463,909 to 169,485,944, reverse strand). Ensembl gene ENSG00000117479.
Subcellular location: Cell membrane
Subcellular location (Human Protein Atlas): Cytosol
Pathways (Reactome):
Metabolism: Vitamin B1 (thiamin) metabolism
Gene Ontology:
Molecular function: protein binding; thiamine transmembrane transporter activity; folic acid transmembrane transporter activity; vitamin transmembrane transporter activity
Biological process: pyridoxine transport; thiamine transport; thiamine transmembrane transport; thiamine-containing compound metabolic process; folic acid transport; spermatogenesis; thiamine diphosphate biosynthetic process; vitamin transport
Cellular component: plasma membrane; membrane
Genetic constraint (gnomAD): Loss-of-function variants: 29 observed, 46.43 expected, observed/expected ratio (o/e) 0.62, 90% interval 0.46 to 0.85. The upper end of that interval is the gene's LOEUF score, 0.85, which puts it in group 3 of 6, group 1 being the genes least tolerant of losing a copy. Missense variants: 566 observed, 627.21 expected, observed/expected ratio (o/e) 0.9, 90% interval 0.84 to 0.97. Synonymous variants: 239 observed, 247.72 expected, observed/expected ratio (o/e) 0.96, 90% interval 0.87 to 1.07.
Homologues: Orthologues: chimpanzee SLC19A2 (100% identical), macaque SLC19A2 (98% identical), rabbit SLC19A2 (95% identical), dog SLC19A2 (92% identical), guinea pig SLC19A2 (92% identical), rat Slc19a2 (91% identical), mouse Slc19a2 (91% identical), pig SLC19A2 (86% identical), tropical clawed frog slc19a2 (66% identical), zebrafish slc19a2 (55% identical), Caenorhabditis elegans folt-1 (34% identical), Drosophila melanogaster CG6574 (31% identical), and 4 more. Paralogues in human: SLC19A3 (49% identical), SLC19A1 (37% identical).
Diseases named in the same sentence as SLC19A2 in open-access papers:
SLC19A2 is named in the same sentence as 48 diseases in open-access papers, as found by Europe PMC text mining. Sharing a sentence is not in itself a finding about the gene and the disease. The quoted sentences say what the papers report.
diabetes (25 papers, 2013 to 2026). "Rogers syndrome (thiamine-responsive megaloblastic anemia, TRMA) is a rare autosomal recessive disorder caused by mutations in SLC19A2 and is characterized by megaloblastic anemia, diabetes and sensorineural deafness." (PMID 41960466, 2026). "Diabetes in a TRMA syndrome is a monogenic form of diabetes owing to SLC19A2 mutations that encode a thiamine conveyor called THTR1 plasma membrane." (PMID 34584998, 2021). "Four genetic defects are reported: three with a predominantly neurological phenotype (SLC19A3, SLC25A19 and TPK1) and one with a multisystem disease (SLC19A2), including megaloblastic anaemia, thrombocytopenia, diabetes and hearing loss." (PMID 32933220, 2020). "With improved access to genetic testing, we expect that more individuals with SLC19A2 mutations will be referred to diabetes clinics." (PMID 29450569, 2018). "SLC19A2 gene mutations causing NDM lead to the development of diabetes, deafness and megaloblastic anemia." (PMID 26839896, 2016). "Diabetes caused by SLC19A2 gene mutations can sometimes be successfully treated with thiamine (n=7)." (PMID 26231457, 2015). "We recommend sequence analysis of the SLC19A2 gene in individuals with a clinical triad of diabetes mellitus, hearing loss, and anemia." (PMID 24072090, 2013). "Thiamine-responsive megaloblastic anemia (TRMA) is an autosomal recessive syndrome characterized by early-onset anemia, diabetes, and hearing loss caused by mutations in the SLC19A2 gene." (PMID 23454484, 2013). "Similarly, certain SLC19A2 mutations cause Thiamine Responsive Megaloblastic Anemia syndrome, characterized by diabetes, hearing loss, and anemia." (PMID 36344967, 2022). "On the previous basis it appears interesting to propose the inclusion of the SLC19A2 gene in the panels of candidate genes used for the diagnosis of complex diseases associating bone marrow failure, diabetes and hearing loss and, possibly, developmental anomalies of heart and bones (microcephaly)." (PMID 31144472, 2019). "Genetic mutations causing SLC19A2 dysfunction can specifically result in outcomes such as megaloblastic anemia (TRMA), sensorineural hearing loss, hyperglycemia, and diabetes mellitus." (PMID 40243711, 2025). "We systematically analyzed evidence for precision treatments for GCK-related hyperglycemia, HNF1A-, HNF4A- and HNF1B-diabetes, and mitochondrial diabetes (MD) due to m.3243 A > G variant, 6q24-transient neonatal diabetes mellitus (TND) and SLC19A2-diabetes." (PMID 39025920, 2024). "Does thiamine supplementation improve glycemia in SLC19A2-diabetes, also known as Thiamine-Responsive Megaloblastic Anemia Syndrome (TRMA)?" (PMID 39025920, 2024). "Limited data support oral agents after relapse in 6q24-TND and for thiamine improving glycemic control and reducing/eliminating insulin requirement in SLC19A2-diabetes." (PMID 39025920, 2024). "Are there alternatives to insulin therapy in 6q24-related transient neonatal diabetes (6q24-TND); and does thiamine supplementation improve glycemia in SLC19A2-diabetes also known as Thiamine-Responsive Megaloblastic Anemia (TRMA) syndrome?" (PMID 39025920, 2024). "Varying data on the effect of thiamine therapy on SLC19A2-diabetes were available for 95 patients (at the individual level, n = 72 patients; at group level n = 23 in one case series)." (PMID 39025920, 2024). "Increased levels of the thiamine transport protein, isoform 1 (THTR1), which is encoded by SLC19A2, are likely to be present in red blood cells (RBCs) and mononuclear leukocytes of patients with diabetes in comparison to healthy subjects." (PMID 37189771, 2023).
diabetes (continued). "Diabetes in SLC19A2 defects, peripheral neuropathy and encephalopathy in SLC19A3, SLC25A19, and TPK1 genetic defects, megaloblastic anemia, and deafness are the five phenotypes associated with inborn errors of thiamine transporters." (PMID 37189771, 2023). "Of the 34 gene panels for MODY/monogenic diabetes listed in the NCBI Gene Testing Registry, only six panels and one panel included WFS1 and SLC19A2, respectively (the two commonest causes in our Turkish cohort)." (PMID 34686905, 2022). "Thiamine-responsive megaloblastic anemia (TRMA), a rare syndrome characterized by diabetes, anemia, and sensorineural deafness was described in 1978, and later associated with a defect in the SLC19A2 gene encoding for thiamine transporter-1 (THTR1)." (PMID 34091762, 2021). "We identified six children with monogenic diabetes, including four novel mutations: homozygous mutations in WFS1 (n=3), SLC19A2 and SLC29A3, and a heterozygous mutation in GCK." (PMID 31276222, 2019). "We identified a nonsense mutation, c.697C > T (p.Gln233*), in SLC19A2 in a series of TRMA patients with congenital/early neonatal hearing loss and neonatal/early childhood diabetes and anemia." (PMID 23454484, 2013). "We recommend thiamine be started as soon as a diagnosis of SLC19A2-diabetes is made." (PMID 39025920, 2024). "Additionally, we recommend close follow-up of patients with SLC19A2-diabetes after the initiation of thiamine treatment to adjust the diabetes treatment if required (grade D evidence)." (PMID 39025920, 2024). "SLC19A2 homozygous mutations have been described as a cause of thiamine-responsive megaloblastic anemia (TRMA), an autosomal recessive syndrome characterized by megaloblastic anemia, diabetes and sensorineural deafness." (PMID 32933220, 2020). "In summary, SLC19A2 mutations are a rare cause of diabetes which can present without anaemia and deafness." (PMID 29450569, 2018). "Human thiamine levels are altered by genetic mutations impacting thiamine transporters: alterations affecting solute carrier family 19-member 2 (SLC19A2) may lead to TRMA, sensorineural hearing loss, hyperglycemia, and diabetes mellitus (DM)." (PMID 40362174, 2025). "Four identified genetic defects cause impaired thiamine transport and metabolism; specifically, the outcomes of SLC19A2 dysfunction due to genetic mutation may include megaloblastic anemia (TRMA), sensory-neural hearing loss (sensorineural deafness), hyperglycemia, and diabetes mellitus." (PMID 40243711, 2025). "This is the first study to analyse the sequence of the MTOR, TBC1D4, CACNA1E, SLC19A2 and KCNH6 genes in Polish patients with suspected MODY-X diabetes using the NGS method." (PMID 38932873, 2024). "The strongest evidence for a precision approach was, in order, HNF1A-diabetes, GCK-related hyperglycemia, relapse of 6q24-TND, and SLC19A2-diabetes." (PMID 39025920, 2024). "There were no randomized trials for therapeutic response in SLC19A2-diabetes, and the scope of the studies was mainly on the overall description of the phenotype." (PMID 39025920, 2024).
Rogers syndrome (15 papers, 2019 to 2026). "Biallelic variants in the SLC19A2 gene, causing Roger syndrome (RS) or thiamine-responsive megaloblastic anemia (TRMA), were detected in three patients (8.11%) from two unrelated families." (PMID 40302952, 2024). "Homozygous, heterozygous or missense mutations in SLC19A2 cause an autosomal recessive condition known as thiamine-responsive megaloblastic anemia (TRMA) or thiamine metabolism dysfunction syndrome 1 or Roger’s syndrome (OMIM 249270)." (PMID 37153911, 2023). "Another rare syndrome is Thiamine-responsive megaloblastic anemia or Rogers syndrome (OMIM#249270), an autosomal recessive disorder caused by mutations in the SLC19A2 gene." (PMID 39408828, 2024). "Thiamine-responsive megaloblastic anemia (TRMA syndrome), also known as Rogers syndrome, is usually associated with non-autoimmune early-onset diabetes mellitus, anemia and sensorineural deafness due to autosomal recessive mutations in the SLC19A2 gene that encodes thiamine transporter." (PMID 36295831, 2022).
Thiamine-responsive megaloblastic anemia (13 papers, 2013 to 2026). A type of megaloblastic anemia (i.e., anemia characterized by the presence of erythroblasts that are larger than normal) that improves upon the administration of thiamine. "SLC19A2 mutations cause thiamine-responsive megaloblastic anemia (TRMA), which is accompanied by hyperglycemia and sensorineural deafness." (PMID 37153911, 2023). "Thiamine-Responsive Megaloblastic Anemia (TRMA) syndrome, caused by mutations in the thiamine transporter gene SLC19A2, presents with a classic triad: megaloblastic anemia, sensorineural deafness, and non-autoimmune diabetes." (PMID 41614934, 2026). "In Thiamine-Responsive Megaloblastic Anemia (TRMA) syndrome, caused by SLC19A2 mutations, the primary defect is intracellular thiamine deficiency due to transporter failure." (PMID 41614934, 2026). "Mutations in the SLC19A2 gene, encoding thiamine transporter 1 (THTR1), were reported to be associated with thiamine-responsive megaloblastic anemia (TRMA), which is characterized by early-onset diabetes mellitus, anemia, and sensorineural deafness." (PMID 35154281, 2022). "A rare cause of megaloblastic anemia (MA) is thiamine-responsive megaloblastic anemia (TRMA), a genetic disorder caused by mutations in SLC19A2 (encoding THTR1), a thiamine transporter." (PMID 33649974, 2021).
anemia (12 papers, 2013 to 2024). A reduction in the number of red blood cells, the amount of hemoglobin, and/or the volume of packed red blood cells. "This work does, however, illustrate the promises and pitfalls of MWAS on peripheral blood DNA in large epidemiological studies, and suggests that the anemia-associated SLC19A2 gene is a mQTL." (PMID 25265411, 2014). "Case 9 (SLC19A2 p.T405A) presented with moderate anemia (hemoglobin, 70 g/L), which improved with oral iron therapy." (PMID 26839896, 2016). "We recommend assessment of TRMA syndrome using SLC19A2 gene analysis in any diabetic patient with anemia or deafness." (PMID 24072090, 2013). "Our patient with SLC19A2 mutation exhibited moderate normocytic anemia with no hearing abnormalities at diagnosis." (PMID 26839896, 2016).
megaloblastic anemia (11 papers, 2013 to 2026). Anemia characterized by the presence of unusually large erythroblasts in the bone marrow called megaloblasts. "Genetic defects in ThTr1 (SLC19A2) and ThTr2 (SLC19A3) result in thiamine-responsive megaloblastic anemia (TRMA) and biotin-responsive basal ganglia disease (BBGD), respectively." (PMID 27379239, 2016).
Thiamine deficiency (8 papers, 2015 to 2025). Thiamine deficiency is a condition that occurs due to not enough thiamine (vitamin B1). "Mutations in thiamine transporter genes, SLC19A2 and SLC19A3, have been observed in cases of thiamine deficiency due to decreased absorption of thiamine that leads to neurological dysfunction." (PMID 32564308, 2020).
breast carcinoma (5 papers, 2013 to 2022). "An increase in the expression of the thiamine transporter, SLC19A2 was found in breast cancer tissue when compared to normal breast tissue." (PMID 30459934, 2018). "We have previously established an increase in the expression of SLC19A2 and TPK1 in breast cancer tissue when compared to normal breast tissue." (PMID 30459934, 2018). "TPK1, SLC19A2/THTR1 and SLC25A19/TPC have been shown to be up-regulated in breast cancer in both patients and cell lines." (PMID 25788274, 2015). "Recently, our group discovered a significant increase in the gene expression of TPK1, SLC19A2, and SLC25A19 in breast cancer tissue samples compared to normal breast tissue." (PMID 24280319, 2013). "Upregulation of TPK-1, SLC19A2, SLC25A19 and downregulation of SLC19A3 was also verified in several breast cancer cell lines compared to human mammary epithelial cells (hMECs)." (PMID 24280319, 2013). "Slc19a2/THTR1 has been shown to be up-regulated in breast cancer and its expression seems to have a negative effect on tumor specific radiosensitization." (PMID 30742630, 2019).
Stroke (3 papers, 2018 to 2025). Sudden impairment of blood flow to a part of the brain due to occlusion or rupture of an artery to the brain. "In the comparison of the controls against each patient group including “random,” “stroke,” and “long survivor” groups, we found PLAT and SLC19A2 [MIM: 603941] to be consistently significant in gene‐specific differences in allele frequencies across all the comparisons." (PMID 32898326, 2020).
beriberi (1 paper, 2025). Beriberi is a condition that occurs in people who are deficient in thiamine (vitamin B1). "The thiamine transporter SLC19A2 (linked to fulminant Beriberi) showed a similar pattern, correlating with changes in cardiac thiamine metabolism and serum thiamine." (PMID 40998786, 2025).
gastric cancer (1 paper, 2011). A primary or metastatic malignant neoplasm involving the stomach. "Previously, we showed that SLC19A3 but not SLC19A2 was frequently down-regulated through promoter hypermethylation in gastric cancer." (PMID 21789241, 2011). "In our previous study of gastric cancer, we showed that SLC19A3 but not SLC19A2 was down-regulated through promoter hypermethylation." (PMID 21789241, 2011).
myopia (1 paper, 2025). "To determine the expression levels of SLC19A2 and SLC19A3 in the choroidal tissues of myopic guinea pigs at different myopia induction times, we performed immunofluorescence staining of the choroidal tissues of myopic guinea pigs." (PMID 40351473, 2025).
osteoporosis (1 paper, 2020). A condition of reduced bone mass, with decreased cortical thickness and a decrease in the number and size of the trabeculae of cancellous bone (but normal chemical composition), resulting in increased fracture incidence. "Furthermore, specific allele combinations of CD320, TCN2, SLC19A1, and SLC19A2 may contribute to increased susceptibility to osteoporosis and OVCF." (PMID 32498429, 2020). "In the present study, we explored possible associations between SNPs located in the 3 ́–UTR of the CD320, TCN2, SLC19A1, and SLC19A2 genes and osteoporosis and OVCFs in 301 postmenopausal women." (PMID 32498429, 2020). "Our analyses therefore suggest that the allelic combinations of CD320, TCN2, SLC19A1, and SLC19A2 genes could play a role in the pathogenesis of osteoporosis and OVCF." (PMID 32498429, 2020). "The genotype and allele frequencies of the CD320 rs9426C>T, TCN2 rs10418 C>T, SLC19A1 rs1051296 G>T, and SLC19A2 rs16862199 C>T SNPs were compared between control subjects and osteoporosis patients with or without OVCF." (PMID 32498429, 2020).
genetic disorder (2 papers, 2018 to 2021). "TRMA is a genetic disorder caused by mutations in SLC19A2 on chromosome 1q23.3, that encodes a thiamine transporter protein." (PMID 29379566, 2018).
SLC19A2 also shares sentences with these, for which no sentence is quoted: deafness (7 papers); Hyperglycemia (5); infection (4); cancer (2); insulin-dependent diabetes (2); microcephaly (2); sensorineural hearing loss (2); tumor (2); Alzheimer disease (1); autism (1); biotin-responsive basal ganglia disease (1); bone marrow failure (1); cardiovascular diseases (1); cerebral infarction (1); diabetic nephropathy (1); Epiphyseal dysplasia (1); hearing loss (1); hypothyroidism (1); immune dysfunction (1); kidney disease (1); Leigh syndrome (1); mitochondrial diabetes (1); neuroblastoma (1); neurodegenerative disease (1); Obesity (1); osteoarthritis (1); progressive polyneuropathy (1); red cell aplasia (1); renal dysfunction (1); schizophrenia (1).
A further 5 diseases each share a sentence with SLC19A2 in 1 paper.